MT1IP (metallothionein 1I, pseudogene )
Synonyms: MT1; MT1I; MTE
Gene: Long non-coding RNA gene on chromosome 16 (56,675,535 to 56,677,883, forward strand). Ensembl gene ENSG00000290663.
Diseases named in the same sentence as MT1IP in open-access papers:
MT1IP is named in the same sentence as 2 diseases in open-access papers, as found by Europe PMC text mining. Sharing a sentence is not in itself a finding about the gene and the disease. The quoted sentences say what the papers report.
liver cancer (1 paper, 2020). An epithelial or non-epithelial malignant neoplasm that arises from the liver. "One of the lncRNAs, MT1IP was reported to act as a tumor suppressor in liver cancer by attenuating cell proliferation and transformation while inducing apoptosis." (PMID 32636408, 2020).
tumour (1 paper, 2020). "Though less obvious, the most promising tumor suppressor network comprise 4 lncRNAs (MT1DP isoforms (NR_027781 and NR_003658) and MT1IP isoforms (NR_003669 and NR_104046)) that are co-expressed with 8 genes in the metallothionein family." (PMID 32636408, 2020). "Nonetheless, one tumor suppressive network comprising 4 tumour suppressor lncRNAs (MT1DP (seqname: NR_027781 and NR_003658) and MT1IP (seqname: NR_003669 and NR_104046)) and 8 co-expressed genes, enriched in the metallothionein family was identified." (PMID 32636408, 2020).